STAT3 (signal transducer and activator of transcription 3)
Diseases named in the same sentence as STAT3 in open-access papers (continued):
Sharing a sentence is not in itself a finding about the gene and the disease.
cervical carcinoma (continued). "To verify the role of STAT3 in cervical cancer cells, we first used CRISPR-CAS9 technique to knock out STAT3 gene in SiHa cells, and verified its efficiency by western blotting." (PMID 35057825, 2022). "Our results showed that OSM stimulation for 24 h increased both the total STAT3 and phosphorylated STAT3 levels in the cervical cancer cell lines (HeLaS3 and SiHa)." (PMID 36551576, 2022). "We also found that tumor-progression-related genes were expressed specific to a subpopulation of tumor cells with a high expression of OSMR and that STAT3 activity induced by OSM was inhibited by SD-36, a STAT3 degrader, in cervical cancer cell lines." (PMID 36551576, 2022). "Oncostatin M (OSM) induces Signal Transducer and Transcription 3 (STAT3) activation, exacerbating cervical cancer." (PMID 36551576, 2022). "This serves to clarify the regulatory mechanism between STAT3 and autophagy and its effect on the proliferation and metastasis of cervical cancer cells." (PMID 35057825, 2022). "Results showed that the positive expression rate of STAT3 in advanced cervical cancer is higher than that in early cervical cancer." (PMID 35057825, 2022). "EGFR, like OSMR, is also known as a biomarker for cervical cancer and induces tumor progression and activation of STAT3." (PMID 36551576, 2022). "The possibility of STAT3 as a targeted therapeutic molecular for cervical cancer is discussed in this study." (PMID 35057825, 2022). "For example, PIAS3 expression negatively correlates with STAT3 signal transduction in cervical cancer (CC) cells, probably by repressing the DNA binding activity of STAT3." (PMID 36557902, 2022). "Hederagenin reportedly mediated cytotoxicity to cancers via multipathways, for example, hederagenin inhibits proliferation and promotes apoptosis of cervical cancer CaSki cells by blocking the STAT3 pathway." (PMID 35388301, 2022). "In order to explore the role of STAT3 in the progression of cervical cancer, we first analyzed the relationship between the expression of STAT3 and LC3B." (PMID 35057825, 2022). "Baicalin showed anti-cancer effects on cervical cancer cells via STAT3 targeting regulated signaling pathways." (PMID 36432119, 2022). "Here, we show that OSM-mediated STAT3 activation promotes pro-tumorigenic gene expression programs, with chromatin remodeling in cervical cancer." (PMID 36551576, 2022). "So, in cervical cancer, does STAT3 affects autophagy level of cervical cancer cells, and in which way it affects the autophagy level of cervical cancer cells?" (PMID 35057825, 2022). "The OSM treatment altered the expression of both total STAT3 and pSTAT3 (Y705 and S727) proteins in cervical cancer cell lines (HeLaS3 and SiHa cells)." (PMID 36551576, 2022). "To examine how OSM-activated STAT3 alters gene expression programs, we performed a transcriptome analysis of cervical cancer cell lines using RNA-seq under the same conditions as the flow cytometry analysis." (PMID 36551576, 2022). "STAT3 was overexpressed in cervical cancer tissues, and negatively correlated with the expression level of LC3B." (PMID 35057825, 2022). "After the in vitro experiment to verify the effect of STAT3 on the proliferation and colony formation of cervical cancer cells, in vivo experiment was carried out in order to be more convincing." (PMID 35057825, 2022). "IL6 can also lead to STAT3 activation, and this pathway contributes to cell proliferation and survival of cervical cancer cells." (PMID 35468924, 2022). "A number of studies have confirmed that STAT3 phosphorylation is also increased in cervical cancer; this is achieved through increased NFκB signalling and autocrine/paracrine activation of STAT3 by the pro-inflammatory cytokine interleukin-6 (IL-6)." (PMID 33427604, 2021). "LINC00240 expression promoted cervical cancer progression via the induction of miR-124-3p/STAT3/MICA-mediated NKT cell tolerance." (PMID 33422052, 2021).
cervical carcinoma (continued). "miR-146b-3p promoted cervical cancer cell proliferation and migration via STAT3 and AKT signaling pathways." (PMID 34321456, 2021). "MUC16 promoted growth and invasion of cervical cancer cells via JAK2/STAT3 phosphorylation-mediated COX-2 expression." (PMID 34150633, 2021). "In cervical cancer, STAT3 has gained importance from the observation that its presence and activity are associated with the malignancy of cervical lesions." (PMID 34445405, 2021). "Res suppresses phosphorylation of STAT3 at tyrosine 705 to impair metastasis of cervical cancer cells." (PMID 34769099, 2021). "LINC00240 acts as an oncogene in cervical cancer progression by modulating the miR-124-3p/STAT3/MICA axis." (PMID 33422052, 2021). "Claudin-9 expression is related to the increased metastatic ability of the hepatocytes by disturbing the TyK2/Stat3 signaling pathway, and it has been related to lymphatic metastasis in cervical carcinoma." (PMID 39296813, 2021). "Based on our results, we suggest that Bazedoxifene is a potent inhibitor of GP130/STAT3 signaling in HPV-positive cervical cancer cells." (PMID 34445405, 2021). "Blocking IL-6 and GP130 signaling in HPV-positive cervical cancer cells abolished STAT3 phosphorylation, and blocking the GP130 signal was found to be a major determinant of STAT3 phosphorylation." (PMID 34445405, 2021). "Stimulation with rhIL‐17 mediated only weak pSTAT3(Tyr705) expression in comparison with the known STAT3 activator Oncostatin M (OSM) in three different cervical cancer cell lines." (PMID 34469022, 2021). "PI3K/Akt, MAPK, NF-κB, and JAK/STAT3 are four classical apoptosis signaling pathways of cervical cancer." (PMID 34395473, 2021). "In cervical cancer, cell invasion and tumor metastasis has been reported to be regulated by miR-125a-5p as it targets STAT3." (PMID 33714953, 2021). "Functional assays in cervical cancer cells revealed that overexpression of MUC16 activated the JAK2-STAT3 signal transducer pathway by STAT3 phosphorylation." (PMID 34150633, 2021). "In cervical cancer, through the ubiquitin-mediated degradation of STAT3, lncRNA-MEG3 can suppress cell survival and cancer growth." (PMID 33435156, 2021). "IL-6 in cervical cancer is a known potential biomarker that acts by inducing vascular epithelial growth factor-dependent angiogenesis in a STAT3-dependent manner and promoting tumor proliferation." (PMID 34445405, 2021). "The ability of Bazedoxifene to inhibit GP130/STAT3 signaling was evaluated in SiHa, HeLa, and CaSki cervical cancer cells." (PMID 34445405, 2021). "Studies have demonstrated that the activation of STAT3 signaling promotes metastasis of cervical cancer cells." (PMID 33040485, 2020). "Western blot was used to examine the effects of RES on the protein levels and phosphorylation status of STAT3 in cervical cancer cells." (PMID 33040485, 2020). "The IL-6 expressed in HPV positive cervical cancer cells then facilitates autocrine STAT3 activation via JAK/IL-6R." (PMID 32915198, 2020). "Resveratrol Suppress growth and Epithelial Mesenchymal Transition of cervical cancer through inhibiting STAT3 Tyr705 phosphorylation." (PMID 33040485, 2020). "STAT3 in cervical cancer has acquired importance from observations showing that its presence and activity are associated with the malignancy of cervical lesions." (PMID 33076315, 2020). "IL-6 signalling has been demonstrated to be upregulated and associated with the activation of STAT3 in both HNSCC and cervical cancer." (PMID 32899142, 2020). "In conclusion, our results demonstrate that the STAT3‐miR‐223‐HMGCS1/TGFBR3 axis functions as a key signaling pathway in cervical cancer progression and provides a new therapeutic target." (PMID 32491253, 2020). "In cervical cancer, several reports show that STAT3 is critical for cell transformation and cycle progression." (PMID 32491253, 2020).
cervical carcinoma (continued). "Our results suggest that RES inhibited the growth and metastatic potential of cervical cancer by suppressing STAT3 Tyr705 phosphorylation." (PMID 33040485, 2020). "Given the fact that IRF1 is a STAT3-inducible mediator for cell death enhancement in cervical cancer cells, it will be interesting to investigate the role of STAT3 and ERp57 in IRF1-depedent surface CRT exposure in the future." (PMID 32326356, 2020). "HeLa and SiHa cells were treated with RES, IL‐6, and their combination, then, their STAT3 Tyr705 was detected to further examine the role of RES in the regulation of STAT3 phosphorylation in cervical cancer cells." (PMID 33040485, 2020). "Our data demonstrated that although E6 is primarily responsible for STAT3 phosphorylation in HPV-containing keratinocytes, all three oncoproteins (E5, E6 and E7) can induce STAT3 tyrosine phosphorylation in HPV- cervical cancer cells." (PMID 32899142, 2020). "For instance, the Rac1‐NF‐κB‐interleukin (IL)‐6 signaling axis regulates autocrine STAT3 activation resulting in cervical cancer development." (PMID 32491253, 2020). "The results suggest that reduced phosphorylation level of STAT3 enhanced the inhibitory effects of RES on the invasion potential of cervical cancer cells." (PMID 33040485, 2020). "The inhibition of STAT3 highlights its importance as a therapeutic target in the treatment of cervical cancer." (PMID 33076315, 2020). "In other hand, exosomal miR‐223 derived from cervical cancer cells induces IL‐6 secretion from monocyte/macrophage, which, in turn, activates STAT3 signals in cervical cancer cells." (PMID 32491253, 2020). "Based on previous reports, STAT3 is a master regulator of the development of most cancers, including cervical cancer." (PMID 32491253, 2020). "HPV positive cervical cancer cells have a higher level of constitutively activate STAT3 compared to HPV-negative cells." (PMID 32527332, 2020). "Other studies have demonstrated that the oncostatin M receptor (OSMR) is frequently over expressed in cervical cancer and its pro-oncogenic effects are mediated by STAT3 activation." (PMID 32899142, 2020). "When cervical cancer cells were treated with IL‐6 which is a major stimulator of STAT3 signaling, the miR‐223 level significantly increased in a dose‐dependent manner." (PMID 32491253, 2020). "In cervical cancer, STAT3 is constitutively activate and correlates with cervical disease progression." (PMID 32899142, 2020). "In this study, the STAT3 phosphorylation status in cervical cancer cells and a mouse xenograft tumor model was investigated after RES treatment." (PMID 33040485, 2020). "For example, through NFκB activity, cervical cancer cells secrete IL-6, which in turn activates STAT3 with a pro-tumoral effect." (PMID 33330068, 2020). "Human papillomavirus (HPV) positive cervical cancer cell lines have also been shown to have elevated pTyr705 STAT3 levels, which is driven by exacerbated IL-6 secretion." (PMID 32915198, 2020). "Taken together, our finding provides the new STAT3‐miR‐223‐TGFBR3/HMGCS1 axis in cervical cancer development." (PMID 32491253, 2020). "In tumor loci, exosomal miR‐223 derived from cervical cancer cells induces interleukin‐6 secretion of monocyte/macrophage, which, in turn, stimulates STAT3 signals." (PMID 32491253, 2020). "In cervical carcinoma, STAT3 upregulates the stem-like characteristics of cervical cancer cells by increasing the expression of the stemness supporting markers such as Sox2, Oct4, and Nanog." (PMID 31935877, 2020). "Whilst blockade of CD109 by siRNA and CRISPR/Cas9 inhibited STAT3 activation in cervical cancer cell lines." (PMID 32507856, 2020). "Here, we show that STAT3 phosphorylation in HPV positive cervical cancer cells is mediated primarily via autocrine activation by the pro-inflammatory cytokine Interleukin 6 (IL-6)." (PMID 31226168, 2019).
cervical carcinoma (continued). "As expected, our results demonstrated that IL-6-induced STAT3 activation was reduced in TMS-TMF-4f-treated cervical cancer cells." (PMID 31816985, 2019). "Characterization of host cell transcription factors has revealed a disease stage and grade-specific expression and activity of some of the key transcription factors like AP-1, NF-κB, and STAT3 in cervical cancer carcinogenesis." (PMID 31487312, 2019). "To investigate if such a positive feedback loop exists in cervical cancer cells we used siRNA to deplete STAT3 from HeLa and CaSKi cells and then measured the impact on IL-6 expression." (PMID 31226168, 2019). "Several studies reported that constitutive and IL-6-induced STAT3 activation is common in cervical cancer cell lines and tissues." (PMID 31816985, 2019). "The increased phosphorylation of STAT3 in HPV positive cervical cancer cells was attributed to an increase in IL-6 expression by HPV E6 and the induction of autocrine/paracrine IL-6/gp130/STAT3 signalling." (PMID 31226168, 2019). "Here, we demonstrate that JAK2 is aberrantly phosphorylated in cervical cancer cells and that inhibition of JAK2 results in the loss of STAT3 phosphorylation." (PMID 31817106, 2019). "Recently, it has been clearly demonstrated that the autocrine and paracrine actions of IL-6 are essential for STAT3 activation in HPV18-positive cervical cancer cell lines (SW756 and HeLa)." (PMID 31470515, 2019). "In cervical cancer, STAT3 has previously been shown to be required for viral oncogene expression and for cell growth." (PMID 31817106, 2019). "To further elucidate the role of STAT3 in TMS-TMF-4f-induced apoptosis, we evaluated the apoptotic effects of TMS-TMF-4f on STAT3-overexpressing cervical cancer cells with pMXs-STAT3C transfection." (PMID 31816985, 2019). "One common mechanism of cisplatin resistance in cancer is the activation of STAT3, including in cervical cancer." (PMID 31817106, 2019). "Evidence from our group and others, indicate the presence of active STAT3 in cervical cancer stem cells." (PMID 31487312, 2019). "As the aberrant activation of the key transcription factor STAT3 is associated with cell survival and proliferation, we examined the effects of TMS-TMF-4f on STAT3 activation in cervical cancer cells." (PMID 31816985, 2019). "Our results showed that TMS-TMF-4f decreased p-STAT3 levels and STAT3-mediated anti-apoptotic proteins including cyclin D1, survivin, and c-Myc in both HeLa and CaSki cervical cancer cells." (PMID 31816985, 2019). "IL-6 and gp130 blocking antibodies were utilised to interrogate their requirement for STAT3 phosphorylation in cervical cancer cells." (PMID 31226168, 2019). "Our previous work demonstrated that the blockade of STAT3 activity with small molecule inhibitors or siRNA depletion of STAT3 protein adversely affected HPV+ cervical cancer cell proliferation and resulted in an increase in apoptosis." (PMID 31817106, 2019). "Recent studies have confirmed the overexpression of STAT3 in cervical cancer tissues and its close relationship with human papillomavirus (HPV) infection, tumor metastasis, and poor prognosis of patients." (PMID 31320837, 2019). "We analyzed the role of MEG3 and STAT3 in cervical cancer and found that these two proteins have overlapping functions in HPV infection and lymphatic metastasis." (PMID 31320837, 2019). "The expression of the pro-survival protein Bcl-XL, whose expression is dependent on STAT3 in HPV+ cervical cancer cells, was also reduced." (PMID 31817106, 2019). "IL-6 has been proven to induce epithelial–mesenchymal transition in human cervical carcinoma cells via STAT3 activation." (PMID 31470515, 2019). "The data presented here demonstrate that NFκB is essential for the induction of IL-6 and the autocrine/paracrine induction of STAT3 phosphorylation in HPV+ cervical cancer cells." (PMID 31226168, 2019).
cervical carcinoma (continued). "ABC294640, the novel, specific and competitive SphK2 inhibitor, in-activated SphK in cervical carcinoma cells, leading to S1P depletion, ceramide production and STAT3 inhibition." (PMID 29416779, 2018). "As a strategy for treatment of cervical cancer, we previously proposed combination therapy with the STAT3 inhibitor S3I-201 and tumor necrosis factor-related apoptosis-inducing ligand (TRAIL), and tested this strategy using SiHa cells." (PMID 29568369, 2018). "Continuously activated STAT3 has been found in many human tumors, such as lung cancer, gastric carcinoma, cervical carcinoma, and meningiomas." (PMID 29423040, 2018). "A previous report demonstrated that knockdown of STAT3 protein in cervical carcinoma cell line by siRNA reduced mRNA and protein expressions of NANOG and SOX2." (PMID 29963272, 2018). "Another study reported that up-regulation of miR-29b suppressed the angiogenesis of cervical cancer cells in vitro and inhibited neovascularization in vivo through targeting Signal Transducer and Activator of Transcription 3 (STAT3) gene." (PMID 29491883, 2018). "NF-kB pathway is an important player in the development of cervical cancer and with STAT3 cooperatively regulates a number of target genes including antiapoptotic and cell cycle control genes, and genes encoding for cytokines and chemokine." (PMID 29945565, 2018). "Our data suggested that TFF3 stimulated an invasive phenotype in cervical cancer cells through STAT3 mediated repression of CDH1." (PMID 28070169, 2017). "In this study, Chen and colleagues showed that Blcap interacted with Stat3 in cervical cancer cell lines, supporting our own observation that Blcap interacts with Stat3 in bladder cancer." (PMID 29190807, 2017). "The overall decline of STAT3 activity in cervical cancer cells can be explained by a decline of the IL-6 binding receptor chain gp80 in cervical cancer cells." (PMID 28895886, 2017). "Restored the expression of miR-29b reduced the mRNA and protein level of STAT3 in HeLa and Caski cervical cancer cells." (PMID 28122338, 2017). "As expected, the phosphorylation level of STAT3 was decreased with JSI-124 treatment in TFF3-overexpressing cervical cancer cells." (PMID 28070169, 2017). "Strikingly, when the IL-6/STAT3-signaling pathway is activated in cervical cancer cells, they are more efficiently killed by chemotherapeutic drugs, such as cisplatin or etoposide." (PMID 28895886, 2017). "This is supported by a recent study in which TFF3 decreased E-cadherin expression in a manner dependent on STAT3 activity, hence promoting the invasiveness of cervical cancer cells." (PMID 29100386, 2017). "The biological function assays showed that overexpression of miR-29b suppressed the invasion, EMT procedure and angiogenesis of cervical cancer cells in vitro and inhibited tumor growth and neovascularization in vivo through targeting STAT3 signal pathway." (PMID 28122338, 2017). "In cultured cervical cancer cells, however, efficient STAT3 activation can only be elicited by IL-6 in the presence of soluble gp80 (sgp80)." (PMID 28895886, 2017). "The whole of data suggests that PI3K/AKT and STAT3 are convergence points of tumorigenic pathways in cervical carcinoma." (PMID 28514765, 2017). "Both leptin and OB3 peptides induced phosphorylation of ERK1/2 and PI3K and phosphorylation of Ser-727 and Tyr-705 of STAT3 in human cervical cancer HeLa cells." (PMID 28750624, 2017). "IL-37 has been shown to suppress cell proliferation and invasion of human cervical cancer (CC) and Renal cell carcinoma (Rcc) through inhibiting STAT3 signaling." (PMID 27835881, 2016). "Meanwhile, IL-6 is one of the key activators of STAT3, so we treated it to cervical cancer cell lines to reveal the relationship among IL-6R/LYN/STAT3." (PMID 27690342, 2016). "All these results indicated that LYN promoted cervical cancer cells metastasis through activating IL-6/STAT3 pathway." (PMID 27690342, 2016).